MIR24-1 (microRNA 24-1)
Synonyms: hsa-mir-24-1; MIR189; MIRN24-1; miR-24-1; miRNA24-1
Gene: MicroRNA gene on chromosome 9 (95,086,021 to 95,086,088, forward strand). Ensembl gene ENSG00000284459.
Pathways (Reactome):
Cellular responses to stimuli: Oncogene Induced Senescence; Oxidative Stress Induced Senescence
Gene expression (Transcription): Transcriptional Regulation by VENTX
Gene Ontology:
Biological process: miRNA-mediated post-transcriptional gene silencing
Cellular component: RISC complex
Homologues: Orthologues: mouse Mir24-1 (99% identical), tropical clawed frog xtr-mir-24a (93% identical), zebrafish dre-mir-24-4 (71% identical). Paralogues in human: MIR24-2 (76% identical), MIR3074 (65% identical).